RBM10 (RNA binding motif protein 10)
Diseases named in the same sentence as RBM10 in open-access papers (continued):
Sharing a sentence is not in itself a finding about the gene and the disease.
cancer (continued). "Since RBM10 was previously shown to inhibit cancer cell proliferation via its effect on alternative splicing, we tested whether RBM10 might reduce c-Myc level by regulating its RNA splicing." (PMID 38032932, 2023). "Interestingly, RBM10 methylation plays a role in promoting or inhibiting cancer in different cancers." (PMID 39282149, 2022). "Next, we assessed the genetic alternations of RBM10 in pan-cancer using cBioPortal tool." (PMID 39282149, 2022). "In summary, this is the first comprehensive pan-cancer research for RBM10." (PMID 39282149, 2022). "However, the RBM10 expression was positively associated with T cell CD4+ Th1 and T cell CD4+ central memory in many cancers, especially in LUAD and LUSC." (PMID 39282149, 2022). "Therefore, the current study is aimed at exploring RBM10 expression profiles and prognosis value in pan-cancer." (PMID 39282149, 2022). "In addition, we also believe that these findings can provide suggestions for further exploring the role and molecular mechanism of RBM10 in different cancers in the future, and we can better understand the role of RBM10 in tumorigenesis." (PMID 39282149, 2022). "The GEPIA2 was utilized for evaluating the prognostic value of RBM10 in TCGA pan-cancer." (PMID 39282149, 2022). "RBM10 mutations can not only affect the progress of cancer but also cause other, non-oncogenic diseases." (PMID 33718153, 2021). "We propose a hypothesis from the perspective of differences in RBM10 expression and molecular structure, which provide new ideas for future experimental research regarding the exact conditions in which RBM10 play a pivotal cancer-inhibiting role." (PMID 33718153, 2021). "Given these different views, it is necessary to summarize the research progress of RBM10 in various fields to reasonably analyze the underlying molecular mechanisms, and provide new ideas and directions for the clinical research of RBM10 in various cancer types." (PMID 33718153, 2021). "Furthermore, our recent study showed that over expression of RBM10 reduces cancer cell migration and the EMT related gene Vimentin as well." (PMID 32947864, 2020). "RBM10 is a multi-domain RNA-binding protein with important functions in development and in cancer." (PMID 28379442, 2017). "Our findings suggest that, since RBM10 levels are increased in many cancers, RBM10 may be a potential therapeutic target for those cancers harbouring elevated KITLG (such as many SCLCs)." (PMID 28728573, 2017). "Therefore, understanding the regulation of RBM10, as well as the range of its downstream effects, is of interest to various areas of cell, developmental and cancer biology." (PMID 28662214, 2017). "Use of our pipeline for the analysis of additional RBM10 mutations in LUAD and other cancers may provide supporting evidence to this proposal." (PMID 28091594, 2017). "Interestingly, among the genes differentially spliced upon RBM10 perturbation in HEK293 cells, several were known factors associated with cancers." (PMID 24000153, 2013). "However, in STAS, PAAD, and THCA, high RBM10 level predicted a better prognosis, which was consistent with previous confirmation of RBM10 might act as a protective factor in certain cancer types." (PMID 39282149, 2022). "Our studies suggested that loss of RBM10 could limit EGFR TKI–induced apoptosis rather than increase the proliferative capacity of cancer cells." (PMID 35579943, 2022). "Therefore, we speculate that RBM10 is also involved in inhibiting the invasion and metastasis of cancer cells." (PMID 33718153, 2021). "However, it has been recently demonstrated that RBM10 can also promote cancer." (PMID 33718153, 2021).
cancer (continued). "We uncovered RBM39 as a new splicing activator and RBM10 as a splicing suppressor of RAC1B in LUAD, which greatly facilitates the understanding of RAC1B splicing regulation and functional significance in cancer." (PMID 40548642, 2025). "Analysing the top 100 co‐expressed genes of UBA1 in pan‐cancer on GEPIA2.0, the top 5 genes (CDK16, ELK1, KDM5C, RBM10 and TBC1D25) were highly correlated with UBA1 in most cancer types." (PMID 39183260, 2024). "Therefore, targeting RBM10 may be a promising immunotherapy strategy for specific cancer." (PMID 39282149, 2022). "And the RBM10 expression is closely related to TMB, MSI, the number of new antigens, and MMR genes in a variety of cancers." (PMID 39282149, 2022). "Inhibition of RBM10 resulted in preferential expression of the full-length, exon 7 retaining, SMN transcript in four cancer cell lines and one normal skin fibroblast cell line." (PMID 28728573, 2017). "RBM10 modulated the alternative splicing of thousands of target genes and may influence the progression of CCA by altering the splicing patterns of cancer-related genes." (PMID 38576051, 2024). "Cancer-derived mutant RBM10-I316F fails to bind to uL18 and uL5 and to inactivate c-Myc, thus incapable of suppressing tumorigenesis." (PMID 38032932, 2023). "As in addition to the classical NAB2-STAT6 fusion, we report four coding variants in cancer-associated genes (BIRC6, KIT, POLQ, and RBM10) which have not been previously reported in SFTs." (PMID 37469410, 2023). "In silico predictions indicated that a metastatic suppressor gene such as KLF17 and two cellular protein, RBM10 and TOX3 which are involved in proliferation and apoptosis of cancer cells could be the actors influencing the outcome of BRAF inhibitor therapy." (PMID 25437182, 2014). "Interestingly, the cancer-derived RBM10-I316F mutant fails to reduce the protein level and activity of c-Myc; instead, this RBM10 mutant appeared to augment the c-Myc level and activity." (PMID 38032932, 2023). "However, the role of RBM10 has not been widely studied in pan-cancer, and its function and potential mechanism in tumors are still unclear." (PMID 39282149, 2022). "We initially utilize The Cancer Genome Atlas (TCGA), Genotype-Tissue Expression (GTEx), Gene Expression Profiling Interactive Analysis 2 (GEPIA2), and Kaplan-Meier (KM) plotter web tools to investigate the RBM10 expression and its clinical prognosis in human pan-cancer." (PMID 39282149, 2022). "It is necessary to know the research status of RBM10 in various fields to determine whether RBM10 plays a positive or negative role in different cancers, and what possible pathways are involved." (PMID 33718153, 2021). "Importantly, a second RRM domain (RRM2) of RBM10 recognizes a C-rich sequence, which explains its known interaction with the intronic 3 ́ site of NUMB exon 9 contributing to regulation of the Notch pathway in cancer." (PMID 28379442, 2017). "However, the RBM10 involvement in pan-cancer immunotherapy is not clear." (PMID 39282149, 2022).
adenocarcinoma (4 papers, 2015 to 2024). A common cancer characterized by the presence of malignant glandular cells. "In one lung study, 12/183 (7%) adenocarcinoma specimens had RBM10 mutations, each patient having a different mutation (5/12 being missense, 5/12 truncating and 2/12 splice-site)." (PMID 25889998, 2015). "Notably, RBM10 exhibited a significantly high mutation frequency (eight tumors, 25%) in stage I–II adenocarcinomas (32 tumors)." (PMID 33139840, 2020). "KRAS, BRAF, STK11/KEAP1, MUTYH/RET, and RBM10/MET-associated modules showed the opposite trend, having significantly higher frequencies of adenocarcinoma cases as genomic alterations increased (P ≤ 0.02)." (PMID 39664186, 2024). "In addition, RBM10 functions to inhibiting the proliferation of non-adenocarcinoma cells." (PMID 33629637, 2021).
infection (2 papers, 2019 to 2025). The state of being infected such as from the introduction of a foreign agent such as serum, vaccine, antigenic substance or organism. "Thus, investigating the interaction of Vpu and RBM10 will give a deeper understanding of Vpu’s role in viral replication and infection." (PMID 40742131, 2025).
neurological disorders (1 paper, 2017). "We identified four genes that had already been associated with neurological disorders (AFF2, ALG13, OPHN1, and RBM10)." (PMID 28769055, 2017).
RBM10 also shares sentences with these, for which no sentence is quoted: hepatocellular carcinoma (3 papers); atrial septal defect (2); intraductal papillary mucinous neoplasm (2); metastasis (2); Talipes equinovarus (2); Alzheimer disease (1); asthma (1); autism spectrum disorder (1); B-cell lymphoma (1); Catel-Manzke syndrome (1); Cerebro-costo-mandibular syndrome (1); cervical cancer (1); chronic myelomonocytic leukemia (1); coagulopathy (1); diabetes mellitus (1); Flavivirus Infections (1); Glass syndrome (1); glioblastoma (1); heart disease (1); Hepatitis B (1); Hepatitis C (1); intrahepatic cholangiocarcinoma (1); lung (1); myelodysplastic syndrome (1); Pan (1); prostate hyperplasia (1); Pulmonary arteriovenous malformation (1); pulmonary fibrosis (1); spinal muscular atrophy (1); Stickler syndrome (1).
A further 2 diseases each share a sentence with RBM10 in 1 paper.